PROKR1 (prokineticin receptor 1)
Description:
Receptor for prokineticin 1. Exclusively coupled to the G(q) subclass of heteromeric G proteins. Activation leads to mobilization of calcium, stimulation of phosphoinositide turnover and activation of p44/p42 mitogen-activated protein kinase. May play a role during early pregnancy.
Synonyms: PK-R1; GPR73; PKR1; ZAQ; GPR73a
Tractability: Small molecule: it belongs to a druggable protein family. Antibody: its Gene Ontology location is reachable by antibodies, with high confidence; UniProt places it where antibodies can reach, with medium confidence; UniProt predicts a signal peptide or a membrane-spanning region. PROTAC: ubiquitination databases record sites on it; a small molecule that binds it is known.
Target class: Peptide growth factor receptor (family A GPCR); Prokineticin receptor; Family A G protein-coupled receptor; Peptide receptor (family A GPCR); Membrane receptor
Gene: Protein-coding gene on chromosome 2 (68,643,579 to 68,658,251, forward strand). Ensembl gene ENSG00000169618.
Subcellular location: Cell membrane
Pathways (Reactome):
Signal Transduction: G alpha (q) signalling events; Peptide ligand-binding receptors
Gene Ontology:
Molecular function: protein binding; G protein-coupled receptor activity; neuropeptide Y receptor activity
Biological process: cellular response to hormone stimulus; circadian rhythm; G protein-coupled receptor signaling pathway; neuropeptide signaling pathway
Cellular component: plasma membrane; membrane
Genetic constraint (gnomAD): Loss-of-function variants: 21 observed, 23.95 expected, observed/expected ratio (o/e) 0.88, 90% interval 0.62 to 1.26. The upper end of that interval is the gene's LOEUF score, 1.26, which puts it in group 5 of 6, group 1 being the genes least tolerant of losing a copy. Missense variants: 548 observed, 543.73 expected, observed/expected ratio (o/e) 1.01, 90% interval 0.94 to 1.08. Synonymous variants: 193 observed, 221.17 expected, observed/expected ratio (o/e) 0.87, 90% interval 0.77 to 0.98.
Homologues: Orthologues: chimpanzee PROKR1 (99% identical), macaque PROKR1 (97% identical), guinea pig PROKR1 (90% identical), pig PROKR1 (90% identical), dog PROKR1 (88% identical), rabbit PROKR1 (85% identical), tropical clawed frog prokr2 (78% identical). Paralogues in human: PROKR2 (85% identical), NPY2R (22% identical), PRLHR (22% identical), NPY4R (21% identical), NPY4R2 (21% identical), NPY5R (21% identical), MCHR1 (20% identical), NPY1R (20% identical), TACR2 (20% identical), TACR1 (20% identical), GPR83 (19% identical), TACR3 (19% identical), and 21 more.
Diseases named in the same sentence as PROKR1 in open-access papers:
PROKR1 is named in the same sentence as 15 diseases in open-access papers, as found by Europe PMC text mining. Sharing a sentence is not in itself a finding about the gene and the disease. The quoted sentences say what the papers report.
Hirschsprung disease (2 papers, 2017 to 2019). Hirschsprung disease (HSCR) is a congenital intestinal motility disorder that is characterized by signs of intestinal obstruction due to the presence of an aganglionic segment of variable extent in the terminal part of the colon. "Genetic mutations in PROKR1 are associated with Hirschsprung's disease [1688], while genetic mutations in PROKR2 are associated with hypogonadotropic hypogonadism with anosmia, hypopituitarism with pituitary stalk interruption [1649] and Hirschsprung's disease [1688]." (PMID 29055040, 2017).
endometrial adenocarcinoma (1 paper, 2009). "In order to investigate the potential role of PROK1 on the induction of angiogenic factors in endometrial cells, we made use of a human endometrial adenocarcinoma Ishikawa cells, stably expressing PROKR1." (PMID 19348862, 2009).
endometrial polyp (1 paper, 2025). A benign nodular lesion protruding above the surface of the endometrium. "*PROKR1 (Fold change = 8.66, p = 0.001925)**: A significant increase in PROKR1 expression is observed in women with endometrial polyps compared to the control group (p < 0.05)." (PMID 39915377, 2025). "In conclusion, this study identified a statistically significant increase in PROKR1 expression in the endometrial tissue of patients diagnosed with endometrial polyps and myoma uteri." (PMID 39915377, 2025). "The results indicate that PROKR1 and PROKR2 exhibit significant changes in expression between women with endometrial polyps and controls, with PROKR1 being upregulated and PROKR2 downregulated." (PMID 39915377, 2025). "In conclusion, this study identified a statistically significant increase in the expression of endometrial PROKR1 in patients diagnosed with endometrial polyps and myoma uteri." (PMID 39915377, 2025). "When the patients diagnosed with endometrial polyp and the healthy controls were compared, it was observed statistically significantly that the expression of PROKR1 increased in endometrium tissue of patients with endometrial polyp (p < 0.05)." (PMID 39915377, 2025). "This suggests that PROKR1 may play a role in the pathology of endometrial polyps, potentially affecting fertility or implantation processes." (PMID 39915377, 2025). "Overall, the figure suggests that while PROKR1 and PROKR2 show the most significant changes, other genes like PROK1, PROK2, and HOXA10 exhibit smaller or non-significant alterations, highlighting the importance of certain prokineticins in the pathology of endometrial polyps." (PMID 39915377, 2025).
lung carcinoma (1 paper, 2013). "Similarly, PROKR1 was previously shown to be involved in cell motility, but it stimulates lung cancer cell migration and promote metastasis." (PMID 23593504, 2013).
Myocardial fibrosis (1 paper, 2017). "Activation of this receptor leads to calcium mobilization and PROKR1, a paralog with unusually high sequence similarity to this receptor, has been associated with insulin-mediated Akt signalling and myocardial fibrosis, diastolic dysfunction and impaired capillary formation." (PMID 28270201, 2017).
myocardial infarction (1 paper, 2022). Gross necrosis of the myocardium, as a result of interruption of the blood supply to the area, as in coronary thrombosis. "Transient PROKR1 gene transfer reduced mortality and preserved left ventricular function by promoting angiogenesis and cardiomyocyte survival in a coronary ligation mouse model of myocardial infarction." (PMID 35722095, 2022).
neuroblastoma (1 paper, 2023). Neuroblastoma (NB) is the most common solid, extracranial childhood tumor. "PROKR1 expression is positively correlated with its ligand in trophoblasts that exhibit a “pseudo-tumorigenesis” feature, and PROKR1 mediates the proliferation of neuroblastoma cells." (PMID 37070074, 2023).
orchitis (1 paper, 2020). Inflammation of one or both testes due to viral or bacterial infections. "After years of exploration, it has been proved that the pathogenesis of orchitis mainly includes inflammatory cytokine imbalance, oxidative stress, apoptosis, and prokineticin 2 (PK2)/prokineticin receptor 1 (PKR1) pathway." (PMID 32922653, 2020).
tumor (2 papers, 2021 to 2023). "These cells produce the Bv8 protein, which is implicated in angiogenesis and stimulates tumor cell migration through activation of the prokineticin receptor 1 (PKR-1)." (PMID 37222464, 2023). "We also describe the potential therapeutic approaches such as vascular endothelial growth factor (VEGF)-B and prokineticin receptor-1 agonists to maintain endothelial function during or following treatments with chemotherapeutic agents, without affecting anti-tumor effectiveness." (PMID 34386529, 2021).
cancer (1 paper, 2015). A tumor composed of atypical neoplastic, often pleomorphic cells that invade other tissues. "G protein-coupled receptors (PROKR1 and PROKR2) are the receptors for PROK1 and are expressed in the endothelial cells and cancer cells themselves." (PMID 25788276, 2015).
metabolic disorders (1 paper, 2025). "Further investigations are warranted to unravel the precise mechanisms involved and to explore the broader metabolic implications of celecoxib‐PROKR1 signalling, which may have implications for therapeutic interventions in muscle‐related conditions and metabolic disorders." (PMID 39887895, 2025).
muscular disorders (1 paper, 2025). "Celecoxib shows promise as a PROKR1 agonist and clinically applicable exercise mimetic for the treatment of muscular disorders." (PMID 39887895, 2025). "In summary, celecoxib offers promise as a novel PROKR1 agonist and a potential therapeutic option for treating muscular disorders." (PMID 39887895, 2025).
PROKR1 also shares sentences with these, for which no sentence is quoted: Infertility (1 paper); Miscarriage (1); Obesity (1).